THBS3 (thrombospondin 3)
Description:
Adhesive glycoprotein that mediates cell-to-cell and cell-to-matrix interactions. Can bind to fibrinogen, fibronectin, laminin and type V collagen.
Synonyms: TSP3
Tractability: Antibody: its Gene Ontology location is reachable by antibodies, with high confidence; UniProt predicts a signal peptide or a membrane-spanning region.
Gene: Protein-coding gene on chromosome 1 (155,195,587 to 155,209,051, reverse strand). Ensembl gene ENSG00000169231.
Subcellular location (Human Protein Atlas): Vesicles; Predicted to be secreted
Pathways (Reactome):
Signal Transduction: Signaling by PDGF
Gene Ontology:
Molecular function: heparin binding; protein binding; calcium ion binding; extracellular matrix structural constituent
Biological process: cell-matrix adhesion; cell adhesion
Cellular component: extracellular matrix; perinuclear region of cytoplasm; extracellular region; thrombospondin complex
Genetic constraint (gnomAD): Loss-of-function variants: 76 observed, 123.12 expected, observed/expected ratio (o/e) 0.62, 90% interval 0.51 to 0.75. The upper end of that interval is the gene's LOEUF score, 0.75, which puts it in group 3 of 6, group 1 being the genes least tolerant of losing a copy. Missense variants: 1,055 observed, 1,308.5 expected, observed/expected ratio (o/e) 0.81, 90% interval 0.77 to 0.85. Synonymous variants: 423 observed, 496.9 expected, observed/expected ratio (o/e) 0.85, 90% interval 0.79 to 0.92.
Homologues: Orthologues: chimpanzee THBS3 (99% identical), macaque THBS3 (99% identical), pig THBS3 (98% identical), dog THBS3 (98% identical), mouse Thbs3 (97% identical), guinea pig THBS3 (97% identical), rat Thbs3 (96% identical), rabbit THBS3 (88% identical), tropical clawed frog thbs3 (80% identical), zebrafish thbs3a (70% identical), zebrafish thbs3b (66% identical), Drosophila melanogaster Tsp (42% identical). Paralogues in human: THBS4 (61% identical), COMP (50% identical), THBS2 (44% identical), THBS1 (43% identical), ISM1 (8% identical).
Diseases named in the same sentence as THBS3 in open-access papers:
THBS3 is named in the same sentence as 50 diseases in open-access papers, as found by Europe PMC text mining. Sharing a sentence is not in itself a finding about the gene and the disease. The quoted sentences say what the papers report.
COVID-19 (7 papers, 2021 to 2024). A disease caused by infection with severe acute respiratory syndrome coronavirus 2. "This ‘coloc-first’ approach identified four proteins (ABO, FAS, OAS1, THBS3) with evidence of genetic colocalisation (PP.H4 >0.8) with four out of seven COVID-19 phenotypes." (PMID 34402426, 2021). "Proteins that exhibited association only in one of the COVID-19 phenotypes included circulating FAS and THBS3." (PMID 34402426, 2021). "Due to its location within the thrombospondin-3 gene, this variant may affect thrombosis related to COVID-19 rather than inflammatory pathways." (PMID 38184750, 2024).
osteosarcoma (7 papers, 2006 to 2025). A usually aggressive malignant bone-forming mesenchymal neoplasm, predominantly affecting adolescents and young adults. "further confirmed that THBS3 is also associated with the development of osteosarcoma, maintaining angiogenesis and promoting tumour development." (PMID 40514348, 2025). "To date, the research about the roles of THBS3 in cancer is poor although THBS3 has been reported to be associated with the prognosis of patients with osteosarcoma and gastric cancer." (PMID 34804159, 2021). "The role of THBS3 and THBS5 in the regulation of cancer growth has only been studied once with respect to THBS3 in osteosarcoma." (PMID 34502094, 2021). "High expression of THBS3 maintains the capacity of angiogenesis and promotes tumor progression in osteosarcoma." (PMID 34804159, 2021). "For the downregulation core gene THBS3, conversely, it was expressed at significantly high levels in osteosarcoma, which was a predictor of worse OS at diagnosis." (PMID 32454908, 2020). "VEGF, THBS3 (thrombospondin 3), osteocalcin, osteonectin, VS38c, and S100 are specific markers for osteosarcoma." (PMID 25310823, 2014). "THBS3, SPARC and SPP1 were identified by cDNA array as genes differentially expressed in osteosarcoma." (PMID 17022822, 2006). "THBS3, SPARC and SPP1 were identified as genes differentially expressed in osteosarcoma." (PMID 17022822, 2006).
osteoarthritis (4 papers, 2016 to 2025). A noninflammatory degenerative joint disease occurring chiefly in older persons, characterized by degeneration of the articular cartilage, hypertrophy of bone at the margins and changes in the synovial membrane. "LOF + MIS variants in ADAMTS6, SPRY2 and COLGALT2 are protective against osteoarthritis, whereas aggregation of these variants in ADAMTSL3, VIT, IL11 and THBS3 confer risk of osteoarthritis." (PMID 40205036, 2025). "Common non-coding sequence variants associated with osteoarthritis phenotypes present concordant directions of effect with gene-burden association results of genes in their vicinity, with the exception of variants near THBS3 and PMVK; these two genes are at the same locus (around 300 kb apart)." (PMID 40205036, 2025). "A study showed that THBS3 was identified as a target gene in the drug treatment of osteoarthritis and the expression of THBS3 was up‐regulated after treatment." (PMID 39428571, 2024).
cardiomyopathy (3 papers, 2019 to 2021). A disease of the heart muscle or myocardium proper. "To more directly prove that reduced integrin membrane content underlies cardiomyopathy associated with Thbs3 induction we employed cardiac-specific transgenic mice overexpressing dimers of α7β1D integrin." (PMID 30622267, 2019). "However, Thbs1 was unique in that it alone caused lethal cardiomyopathy leading us to investigate more deeply into the ER stress response in the Thbs1 and Thbs3 transgenic hearts." (PMID 34168130, 2021). "Interestingly, Thbs3 uniquely leads to loss of integrin attachment complexes at the sarcolemma in promoting cardiomyopathy while Thbs4 augments membrane content of integrin and dystrophin-glycoprotein attachment complexes as part of its protective profile." (PMID 34168130, 2021). "Here the authors show that thrombospondin 3 exacerbates injury-induced cardiomyopathy and promotes destabilization of the cardiomyocyte membrane by impairing integrin trafficking to the sarcolemma." (PMID 30622267, 2019).
gastric cancer (3 papers, 2021 to 2025). A primary or metastatic malignant neoplasm involving the stomach. "However, decreased expression of “GPX1” (OR 2.35; 95% CI 1.63–3.39; P = 5.42 × 10−6) and “THBS3” (OR 1.50; 95% CI 1.30–1.73; P = 3.30 × 10−8) were found to be associated with the higher risk of lung cancer and gastric cancer." (PMID 38659038, 2024). "THBS3 activated PI3K/AKT/mTOR signaling through protein kinase B (PKB) in gastric cancer." (PMID 40941410, 2025). "In gastric cancer, THBS2 is positively correlated with THBS1, THBS3, and THBS4." (PMID 34804159, 2021).
glioma (3 papers, 2020 to 2022). A benign or malignant brain and spinal cord tumor that arises from glial cells (astrocytes, oligodendrocytes, ependymal cells). "THBS3, ATP6VOE, and LINC01235 were significantly upregulated while USP32P2, RTN3, and LINC00294 were markedly downregulated in glioma compared to controls." (PMID 32978519, 2020).
gout (3 papers, 2023 to 2024). A condition characterized by painful swelling of the joints, which is caused by deposition of urate crystals. "At the protein level, SMR analysis revealed significant causal associations between IL2RB, NRBP1, SUMF1, and THBS3 levels and the risk of gout." (PMID 39734218, 2024). "A review article, for instance, described the complicated connection between uric acid, gout, and brain disease, and mentioned the THBS3 gene as a gene associated with uric acid metabolism and gout, with variants affecting uric acid excretion and deposition." (PMID 38831441, 2024). "This study identified 17 genetic loci associated with gout, including four genes related by protein-protein interaction network (PPI) analysis: TRIM46, THBS3, MTX1 and KRTCAP2." (PMID 38831441, 2024). "We identified 17 association signals for gout at unique genetic loci, including four genes related by protein-protein interaction network (PPI) analysis: TRIM46, THBS3, MTX1, and KRTCAP2." (PMID 38831441, 2024). "Given the conflicting directions of IL2RB and THBS3 effects at the gene and protein levels, further exploration of their roles in gout is warranted." (PMID 39734218, 2024). "Eight potential therapeutic targets (ALDH3B1, FCGR2B, IL2RB, NRBP1, RCE1, SLC7A7, SUMF1, THBS3) for gout were identified in the discovery cohort using MR analysis." (PMID 39734218, 2024). "Notably, IL2RB and THBS3 have contradictory directions of effect on gout at the protein and transcriptional levels." (PMID 39734218, 2024). "Nevertheless, there are limited studies on THBS3 and IL2RB in gout and more studies are needed to clarify." (PMID 39734218, 2024).
cardiac hypertrophy (2 papers, 2019 to 2025). "For example, Thbs3−/− mice showed significantly less cardiac hypertrophy following 12 weeks of TAC stimulation compared with wildtype (WT) mice." (PMID 30622267, 2019).
clear cell renal cell carcinoma (2 papers, 2024 to 2025). "Interestingly, the proliferative effect observed upon THBS3 silencing in bovine MuSCs directly contrasts with its reported role as a tumor suppressor in clear cell renal cell carcinoma (ccRCC)." (PMID 40941410, 2025). "THBS1, THBS2 and THBS5 proteins exhibited relatively high expression in six cancer types compared to normal samples, except for THBS5 in clear cell renal cell carcinoma (CCRCC), while THBS3 and THBS4 proteins showed lower levels in colon adenocarcinoma (COAD) and HNSC." (PMID 39732719, 2024).
colon adenocarcinoma (2 papers, 2021 to 2024). "THBS2, THBS3, THBS4, and THBS5 were differentially expressed in TGCT (testicular germ cell tumors) and COAD (colon adenocarcinoma)." (PMID 34804159, 2021).
colorectal cancer (2 papers, 2021 to 2025). A primary or metastatic malignant neoplasm that affects the colon or rectum. "As for AGRN and THBS3, we have not found evidence on their role in colorectal cancer pathogenesis." (PMID 34938324, 2021).
myocardial infarction (2 papers, 2019 to 2021). Gross necrosis of the myocardium, as a result of interruption of the blood supply to the area, as in coronary thrombosis. "A similar augmentation in disease was observed when Thbs3 DTG animals were subjected to myocardial infarction (MI) injury over 4 weeks, showing increased heart size and a greater loss in ventricular performance with enhanced ventricular dilation compared with tTA controls." (PMID 30622267, 2019).
Atrophy (1 paper, 2021). Any weakening or degeneration, especially through lack of use. "Here we show that Thbs1, but not Thbs2, Thbs3 or Thbs4, induces lethal cardiac atrophy when overexpressed." (PMID 34168130, 2021).
chronic kidney disease (1 paper, 2021). Impairment of the renal function secondary to chronic kidney damage persisting for three or more months. "Both THBS3 and MTX1 were tubular-specifically expressed, and the expressions were greatly downregulated in chronic kidney disease." (PMID 33627123, 2021).
colon cancer (1 paper, 2021). "Correlation analyses using TCGA data showed that THBS2 is significantly positively correlated with THBS1, THBS3, THBS4, and THBS5 in colon cancer." (PMID 34804159, 2021).
coronary heart disease (1 paper, 2024). "A study found that THBS3 mediated 19.23% of the association between hyperuricemia and coronary heart disease." (PMID 39734218, 2024).
diabetes (1 paper, 2019). "GTEx indicated possible eQTLs in diabetes-related tissues (liver: GBAP1 p = 1.6 × 10−11, THBS3 p = 2.5 × 10−6; pancreas: GBAP1 p = 3.3 × 10−25, THBS3 p = 5.2 × 10−11, GBA p = 6.3 × 10−8)." (PMID 30976018, 2019).
endocrine cancers (1 paper, 2025). "Further analysis of additional ECM molecules, including VTN, EMC1, THBS3, and CLEC3B revealed a positive correlation trend with PEBP1/STK11 co-expression in endocrine cancers, while correlations in other cancer types varied, suggesting a context-dependent relationship." (PMID 40806276, 2025).
keloid (1 paper, 2021). An irregularly shaped, elevated mark on the skin caused by deposits of excessive amounts of collagen during wound healing. "By comparing the data with the keloids ECMs, we found some of the components, e.g., SLPI, THBS3, show both high expression trends in keloids and in elderly skin, indicating these ECMs could share similar functions in elderly and keloids skin tissue." (PMID 34901026, 2021).
lung adenocarcinoma (1 paper, 2021). A carcinoma that arises from the lung and is characterized by the presence of malignant glandular epithelial cells. "THBS3 was mainly downregulated in 13 types of cancers, including COAD, LUSC, and LUAD (lung adenocarcinoma)." (PMID 34804159, 2021).
mood disorder (1 paper, 2021). A cognitive disorder a disturbance in which the person's mood is hypothesized to be the main underlying feature. "TSP-3 functions in the brain are largely unknown; nevertheless, we have recently found a positive correlation between high THBS3 mRNA in blood and deficits in executive function, attention, behavioral and mood disorders in patients with inborn errors of amino acid metabolism." (PMID 33546327, 2021).
Obesity (1 paper, 2020). Accumulation of substantial excess body fat. "Other members of the EC matrix—thrombospondins—such as those identified in our study (THBS2, THBS3, and THBS4), are mainly detected in visceral adipose tissues and their increased expression level is associated with obesity." (PMID 32485856, 2020).
osteoporosis (1 paper, 2025). A condition of reduced bone mass, with decreased cortical thickness and a decrease in the number and size of the trabeculae of cancellous bone (but normal chemical composition), resulting in increased fracture incidence. "Collectively, these findings underscore the capacity of THBS3 to mitigate age‐related bone loss and delay the progression of osteoporosis in OVX mice by promoting osteoblast activity and reducing adipogenesis and osteoclastogenesis." (PMID 40514348, 2025). "Collectively, these results suggested that THBS3 delayed the progression of osteoporosis and plays a pivotal role in regulating the vascular‐osteogenic coupling crosstalk network in the bone marrow." (PMID 40514348, 2025). "THBS3 could down‐regulate the expression of its downstream target CD47 and delay the process of bone loss in aged mice and OVX mice, which may provide a novel frontier for the treatment of osteoporosis." (PMID 40514348, 2025).
ovarian carcinoma (1 paper, 2022). A malignant neoplasm originating from the surface ovarian epithelium. "A treatment that combines engineered CAR-T cells targeting CD47 and inhibits secreted THBS2/THBS3 using antibodies may constitute a valuable therapeutic strategy to inhibit ovarian cancer progression." (PMID 36352420, 2022).
pancreatic cancer (1 paper, 2021). "In pancreatic cancer, THBS2 is correlated with THBS1, THBS3, and THBS5." (PMID 34804159, 2021).
squamous cell lung carcinoma (1 paper, 2025). A carcinoma arising from squamous bronchial epithelial cells. "Among shared risk genes, THBS3 (thrombospondin 3) and EIF3CL (eukaryotic translation initiation factor 3 subunit C-like) show particularly strong associations with both diseases, possibly representing key molecular nodes connecting RA pathophysiology with squamous cell lung cancer development." (PMID 41327467, 2025).
uterine corpus endometrial carcinoma (1 paper, 2021). A endometrial carcinoma (disease) that involves the body of uterus. "P305Lfs∗181, one of the hotspot mutations of THBS3, was detected in six patients with STAD or UCEC (uterine corpus endometrial carcinoma), and this change was damaging." (PMID 34804159, 2021).
viral infection (1 paper, 2023). "Considering the direct interaction between gD and THBS3 during PRV infection, and the multiple roles of THBS3 in viral infection, the potential of THBS3 as an antiviral target in vivo needs further exploration in the future." (PMID 38089700, 2023).
cancer (14 papers, 2009 to 2025). A tumor composed of atypical neoplastic, often pleomorphic cells that invade other tissues. "Copy number variants (CNVs) level of THBS3 was significantly positively correlated with its mRNA level in 24 of 32 cancer types." (PMID 39732719, 2024). "We mainly found that THBS1, THBS2, and THBS3 are dysregulated in various cancers, and their expression level is associated with the prognosis of patients." (PMID 34804159, 2021). "Except for THBS3, the expression of other TSPs was significantly different between health and cancer tissue." (PMID 38827236, 2024). "Other upregulated genes (e.g., THBS3, SPARC, and SPP1) have also been implicated in cancer cell invasiveness." (PMID 35205840, 2022). "Collagens, MIF, MDK, APP, and laminin were detected as the most significant signaling, and the top ligand-receptor interactions THBS2/THBS3 (CAFs)—CD47 (cancer cells), MDK (CAFs)—NCL/SDC2/SDC4 (cancer cells) as potential therapeutic targets." (PMID 36352420, 2022). "FAS, C16orfS4, FBXO31, ACSS3, ZCCHC8 and THBS3 were found to help the metastatic cancer cells survive from the immune surveillance." (PMID 35685372, 2022). "Using pan-cancer data, we found that THBS3 is downregulated in 13 kinds of cancers while overexpression of THBS3 predicts poor outcomes in 11 kinds of cancer." (PMID 34804159, 2021). "Using the TCGA PanCancerAtlas for Mutual Exclusivity analysis of pan-cancer mutations, we uncovered cooccurrence relationships of THBS2, THBS4, and THBS5 with THBS1; THBS4, THBS3, and THBS5 with THBS2; and THBS3 and THBS4 with THBS5." (PMID 34804159, 2021). "In addition, among these top interactions, we found THBS2/THBS3 secreted by myCAF2 targeting CD47 of cancer cells." (PMID 36352420, 2022). "Our findings revealed that cancer had lower expression of THBS1, THBS3, and THBS4 compared to normal tissue, whereas the expression of THBS2 was higher." (PMID 38827236, 2024). "THBS3 and THBS4 expression exhibited the same trend in most cancer types, albeit with variable degrees of significance in cancer types." (PMID 39732719, 2024). "Recent cancer studies have found that the thrombospondin (THBS) family, including THBS1, THBS2, THBS3, THBS4, and THBS5, play vital roles in the development and progression of human cancers." (PMID 34804159, 2021). "Among these, we found interactions that may constitute potential targets for CAFs-based therapies, such as THBS2/THBS3 (myCAF2) and CD47 (cancer cells) or between MDK (CAFs) and SDC2/SDC4/NCL (cancer cells)." (PMID 36352420, 2022). "It needs to be further explored whether other THBS genes, including THBS3, THBS4, and THBS5, participate in modulating cancer cell EMT and metastasis in the future study." (PMID 34804159, 2021). "Interestingly, THBS3 is also be predicted to participate in the activation of EMT and immune cell infiltrations in human cancers." (PMID 34804159, 2021). "Interestingly, the methylation level of THBS3 was generally inversely correlated with its mRNA level, whereas others did not exhibit a significant correlation in most cancers." (PMID 39732719, 2024).